CACNA1C (calcium voltage-gated channel subunit alpha1 C)
Diseases named in the same sentence as CACNA1C in open-access papers (continued):
Sharing a sentence is not in itself a finding about the gene and the disease.
schizophrenia (continued). "Additionally, CACNA1C variants have been linked to psychiatric disorders such as schizophrenia, bipolar disorder, and major depressive disorder, as well as a range of neurological conditions including ataxia, epilepsy, intellectual disability, and hypotonia." (PMID 41177904, 2025). "In addition, a recent meta-analysis study reported rs1006737, rs2007044 and rs4765905 of the CACNA1C gene to be associated with susceptibility to schizophrenia." (PMID 40259965, 2025). "Gene CACNA1C is a susceptibility gene for schizophrenia according to meta-analysis and GWAS." (PMID 39202013, 2024). "Along these lines, sex-specific effects have also been reported for disease-associated CACNA1C SNPs, with female risk allele carriers showing, e.g., impaired recovery from schizophrenia-spectrum episodes, greater hostility, and harm avoidance as well as increased frequency of paranoia." (PMID 39370418, 2024). "Common variants in CACNA1C have also been strongly associated with other neuropsychiatric disorders including schizophrenia, bipolar disorder and attention deficit hyperactivity disorder, suggesting that CaV1.2 is a key susceptibility factor for neuropsychiatric conditions." (PMID 38658687, 2024). "In BD patients, seven disease-associated SNPs are present within this intron 3 enhancer that could modify histone binding and alter CACNA1C mRNA expression, as has been reported for schizophrenia-associated SNPs also present within this region." (PMID 36803254, 2023). "First, there is now robust genomic evidence that common variants in VGCC subunit genes, notably CACNA1C which encodes the L-type calcium channel (LTCC) CaV1.2 subunit, are trans-diagnostically associated with psychiatric disorders including schizophrenia and bipolar disorder." (PMID 36154842, 2022). "Cacna1c has been associated with schizophrenia and bipolar disorder in human GWAS." (PMID 35237186, 2022). "This includes two major findings: Unmedicated schizophrenia patients with previously identified genetic risk status for schizophrenia in CACNA1C rs2239063 A > C and five KCNH2 SNPs in strong LD demonstrate significant altered HR dynamics and QTvi compared to non-risk genotypes in these patients." (PMID 36421807, 2022). "Genetic risk in CACNA1C, as one of the most established susceptibility genes for schizophrenia, may also have an impact on cardiac autonomic function in schizophrenia patients." (PMID 36421807, 2022). "Specifically, there was particularly strong evidence that the cis-acting SNPs used to construct the CACNA1C model shared a causal variant with schizophrenia in the cerebellum (PPH4 = 0.946), with slightly weaker support for this also in the substantia nigra (PPH4 = 0.777)." (PMID 36055211, 2022). "However, given that the genomic evidence has been collected using current diagnostic criteria and that the most robust associations are seen for CACNA1C, we focus here on CACNA1C’s involvement in psychosis (schizophrenia and bipolar disorder)." (PMID 36154842, 2022). "Among them, MIR137, a micro-RNA, which is a regulator of neuronal development, showed the strongest association in schizophrenia (p-value = 1.6 × 10−11), and three more loci (CACNA1C, ANK3, and ITIH3-ITIH4) were significantly associated with both BD and schizophrenia." (PMID 34502224, 2021). "As an example, our assay enabled functional annotation of 17 intronic CACNA1C amplicons spanning regions harboring schizophrenia- and bipolar disorder-associated SNPs within strong linkage disequilibrium and identified three regions with enhancer activity in the brain." (PMID 34605404, 2021). "Therefore, we conducted a comprehensive meta-analysis on the association between the CACNA1C rs1006737, rs2007044, and rs4765905 polymorphisms and schizophrenia." (PMID 32770953, 2020). "Therefore, we performed an updated comprehensive meta-analysis on the relationship between CACNA1C gene polymorphisms and schizophrenia, which included case-control studies." (PMID 32770953, 2020).
schizophrenia (continued). "Interestingly, the most strongly associated schizophrenia gene in this study, CACNA1C, was also strongly enriched with common variant associations for BIP." (PMID 32398653, 2020). "22, we found evidence that CACNA1C (12p13.33), with well-replicated associations with psychiatric and developmental disorders, may be involved in hypomania, schizophrenia, and bipolar disorder." (PMID 32152294, 2020). "Given the inconsistent association results, whether CACNA1C rs1006737 is associated with schizophrenia remains to be elucidated." (PMID 31033230, 2019). "Furthermore risk allele AA for schizophrenia increases L-type voltage-gated calcium channel current density and levels of CACNA1C mRNA in induced human neurons." (PMID 28792954, 2017). "In addition, both REEP3 and CACNA1C, which score high in this study, also significantly associate with schizophrenia and act in calcium signaling, a downstream pathway of HTR2A55–57." (PMID 29042551, 2017). "These targets have been postulated to include transcripts from many schizophrenia associated genes, such as CACNA1C, and thus MIR137 has been highlighted as a potential modulator of CNS function that could reveal underlying schizophrenia biology." (PMID 27913161, 2017). "Previous studies demonstrated that CACNA1C was associated with schizophrenia." (PMID 26204268, 2015). "Moreover, other independent studies replicated the association of the specific SNP rs1006737 in CACNA1C with schizophrenia in white subjects of self-identified European descent, Danish subjects, and Spanish population, respectively." (PMID 26204268, 2015). "Notably, the latest large-scale genome-wide association study shows that CACNA1C is ranked fourth in terms of the degree of association (p-value) with schizophrenia out of 108 schizophrenia-associated genetic loci." (PMID 26136667, 2015). "The risk variant (rs1006737: A allele) is significantly associated with bipolar disorder and schizophrenia, supporting the hypothesis that CACNA1C contributes to the genetic overlap between these psychiatric disorders." (PMID 25290268, 2014). "Ion channelopathies are known to underlie some epilepsies and it has been shown that variation within the gene CACNA1C (encoding a subunit of the L-type voltage dependent calcium channel) is associated with schizophrenia as well as depression and bipolar affective disorder." (PMID 24625201, 2014). "Subsequent studies also reported association between CACNA1C and schizophrenia (SZ) and major depressive disorder (MDD), thereby supporting the hypothesis of genetic overlap between these severe psychiatric disorders." (PMID 23437284, 2013). "A genetic overlap between ASD, bipolar disorder, and schizophrenia has been hypothesized, and CACNA1C has previously been associated with bipolar disorder in two GWAS." (PMID 23241247, 2012). "Among the CACNA1C variants, rs1006737 and rs4765905 demonstrated high predicted regulatory activity, with RegulomeDB scores of 1f and 2b, respectively, and have been consistently implicated in neuropsychiatric disorders such as autism, schizophrenia, and epilepsy." (PMID 40725423, 2025). "Moreover, rare variants in CACNA1C have also been implicated in schizophrenia." (PMID 36421807, 2022). "In the overall analysis, rs1006737 was associated with the risk of schizophrenia in all five genetic models, and rs2007044 and rs4765905 were also related to schizophrenia in the allele model, implying that the CACNA1C gene may influence the risk of schizophrenia." (PMID 32770953, 2020). "According to the neurodevelopmental hypothesis of schizophrenia, any factor that can affect the development of the nervous system may be the cause of schizophrenia; thus, the CACNA1C gene may be involved in schizophrenia by regulating the development of the nervous system." (PMID 31033230, 2019).
schizophrenia (continued). "Single-nucleotide polymorphisms (SNPs) in CACNA1C, the α1C subunit of the voltage-gated L-type calcium channel Cav1.2, rank among the most consistent and replicable genetics findings in psychiatry and have been associated with schizophrenia, bipolar disorder and major depression." (PMID 28696432, 2018). "Furthermore, CACNA1C was also associated with schizophrenia." (PMID 26204268, 2015). "miR-137 regulates key schizophrenia-associated genes, including NRGN and CACNA1C, affecting neural development and function." (PMID 40779062, 2026). "In recent years, the clinical phenotypes related to CACNA1C have been increasingly complex, including schizophrenia, bipolar disorder, epilepsy, migraine, and ataxia." (PMID 41177904, 2025). "Additionally, the CACNA1C risk variant rs1006737 is associated with reduced white matter integrity in the frontal, parietal, and temporal regions and the cingulate gyrus of individuals with schizophrenia, indicating its impact on brain structure and function in this disorder." (PMID 40004081, 2025). "Schizophrenia and OCD share several gene polymorphisms (e.g., CACNA1C, COMT, and 5-HTTLPR), but schizophrenia still possesses other genetic polymorphisms distinct from those seen in OCD." (PMID 38814466, 2024). "CACNA1C is a well-described risk gene for psychiatric disorders such as bipolar disorder, MDD, and schizophrenia." (PMID 36865068, 2023). "The differences between the siblings and HC were seen in GRM3 and CACNA1C, and the differences between the siblings and schizophrenia were limited to CACNA1C." (PMID 37158213, 2023). "In the present study, we provide first support for the impact of the two candidate susceptibility genes, CACNA1C and KCNH2, on CADF in schizophrenia." (PMID 36421807, 2022). "The alpha 1C subunit of CaV1.2 is encoded by the gene CACNA1C, which has been robustly linked to increased risk for many neuropsychiatric disorders including autism, schizophrenia, major depression, and bipolar disorder." (PMID 36550186, 2022). "Given the possible association of CACNA1C and KCNH2 with CADF in schizophrenia, we searched the literature for significant associations with cardiac autonomic traits, QT prolongation, and/or schizophrenia." (PMID 36421807, 2022). "Schizophrenia GMV deficits in the hippocampus, temporal gyrus, and cerebellum are associated with genetic factors such as SATB2, GABBR2, and CACNA1C." (PMID 35717212, 2022). "Regarding this, we report a potential role for CACNA1C in this feasible physiological mechanism linking cardiovascular disease and schizophrenia." (PMID 36421807, 2022). "Reassuringly, many recapitulated genes are well-established for the traits, such as CACNA1C for schizophrenia, TCF7L2 for T2D, APOB for lipids, and STAT4 for autoimmune diseases." (PMID 33990562, 2021). "Several of these genomic markers are shared between BD and schizophrenia such as CACNA1C, CACNB2, NCAN, TRANK1, ITIH3-ITIH4, and ANK3." (PMID 34502224, 2021). "Enhancers from schizophrenia GWAS regions were found to interact with the promoters of a number of genes (DRD2, GRIN2A, CACNA1C, and FOXP1), which have previously been unambiguously linked to schizophrenia." (PMID 31963710, 2020). "Based on these findings, we were curious to see if the CACNA1C gene had the same effect on schizophrenia in Asians as it did in the Europeans." (PMID 32770953, 2020). "All four family members were either homozygous or heterozygous for the bipolar risk genotypes in the SYNE1, ANK3, CACNA1C, ODZ4 (TNM4) and ZNF804A genes, of which ZNF804A is also a schizophrenia risk allele." (PMID 32377792, 2020). "In fact, previous genome-wide association studies have shown that Cav1.2 gene (CACNA1C) polymorphisms are associated with MDD, bipolar disorder, and schizophrenia." (PMID 30760886, 2020).
schizophrenia (continued). "Variants in the CACNA1C voltage-gated calcium channel (VGCC) gene are common risk factors for autism and other neurodevelopmental disorders including schizophrenia, bipolar disorder and attention deficit hyperactivity disorder (ADHD)." (PMID 31805042, 2019). "Nine studies including two European‐decent samples and seven Asian cohorts contributed 12,744 cases and 16,460 controls for the analysis of CACNA1C rs1006737 and schizophrenia." (PMID 31033230, 2019). "There are additional genes implicated in schizophrenia, bipolar disorder and autism spectrum disorder such as NRXN1, CACNA1C, CACNB2 and CNTNAP2." (PMID 29794033, 2018). "A recent trans-ancestry meta-analyses of Chinese and PGC2 samples (a total of 43,175 cases and 65,166 controls) further supports the association between CACNB2, CACNA1C, CACNA1I genes and schizophrenia." (PMID 29308060, 2018). "CACNA1C and ZNF804A are two genes that have been implicated in schizophrenia and affective disorders through multiple studies, including GWAS and case/control brain expression analyses." (PMID 30142156, 2018). "The cross-disorder risk gene CACNA1C is strongly implicated in multiple neuropsychiatric disorders, including autism spectrum disorder (ASD), bipolar disorder (BPD) and schizophrenia (SCZ)." (PMID 29739816, 2018). "The malfunctioning REM-sleep processes of heterozygous CACNA1C knockout mice resemble the impaired sleep regulation observed in schizophrenia." (PMID 28792954, 2017). "These included replicated risk variants for schizophrenia associated with imaging phenotypes before, for example, rs11696094 (ZNF804A; ToM, RP), rs2007044 (CACNA1C; EM, RP), rs1702294 (miR137; EM) and rs9636107 (TCF4; EM)." (PMID 28072415, 2017). "Preclinical studies supported a role of CACNA1C in the pathogenesis of mood disorders and the gene was associated with MDD, bipolar disorder, schizophrenia and autism spectrum disorders." (PMID 27091189, 2016). "TOP2B2 peaks from untreated cells are associated with three genes (CNTN4, IMMP2L and SATB2) implicated in both autism and schizophrenia whilst TOP2B2 peaks from E2-treated cells are associated with five genes (CNTN4, IMMP2L, EPC, SMG6 and CACNA1C)." (PMID 26459242, 2015). "A previous GWAS demonstrated that rs4765905 in CACNA1C reached genome-wide significance in 16,374 cases with schizophrenia, schizoaffective disorder or bipolar disorder and 14,044 controls (p = 7.0×10−9)." (PMID 26204268, 2015). "It has been shown that genes related to Ca2+ signaling, such as the CACNA1C, CACNB2, and CACNA1I genes that encode VGCC subunits, are associated with schizophrenia and other psychiatric disorders." (PMID 26136667, 2015). "In two accompanying papers, five schizophrenia susceptibility genes including CSMD1, C10orf26, CACNA1C, TCF4, and ZNF804A were validated as miR-137 targets, providing additional evidence for the involvement of miR-137 in schizophrenia." (PMID 25250332, 2014). "In schizophrenia, both CACNA1C and ANK3 were identified, and in bipolar disorder TRANK1 and CACNB2 were also significantly associated." (PMID 23637625, 2013). "Results for CACNA1C SNP rs1006737 (AA+AG>GG) effect on amygdala activation in a sample of bipolar disorder and schizophrenia cases and healthy controls." (PMID 23437284, 2013). "Of interest, the ITIH3 region (3p21.1), ANK3 (10q21) and CACNA1C (12p13.3) were discovered previously in the same, combined schizophrenia and bipolar disorder sample." (PMID 23637625, 2013). "It targets genes and is essential for controlling synaptic plasticity, such as NRGN and CACNA1C, which are involved in neural development and synaptic function, contributing to the neurodevelopmental hypothesis of schizophrenia." (PMID 40779062, 2026). "Indeed, fine-mapping and eQTL analysis from the largest schizophrenia GWAS to date identified CACNA1C as a key candidate contributing to the enrichment of gene sets relevant to synaptic function associated with disease." (PMID 40565009, 2025).
schizophrenia (continued). "Moreover, CACNA1C emerged as the hub gene in the PPI network formed from genes with higher expression in brain regions with ECM alterations in schizophrenia." (PMID 38491019, 2024). "However, functional magnetic resonance imaging (fMRI) revealed amygdala activation during emotional processing both in healthy carriers of the CACNA1C rs1006737 risk allele and people with BAD and schizophrenia." (PMID 38328521, 2023). "An example of a relatively highly studied gene → behavioral endophenotype → disease pathway is that of the Calcium Voltage-Gated Channel Subunit Alpha1 C (CACNA1C) gene, which is a known susceptibility gene for several psychiatric disorders including schizophrenia." (PMID 36457050, 2022). "Hence, we suggest a potential association between CACNA1C and KCNH2 variants and CADF in schizophrenia, which needs to be replicated in larger cohorts with higher statistical power." (PMID 36421807, 2022). "Furthermore, rs1006737 or the CACNA1C and rs1344706 ZNF804A were commonly associated with schizophrenia and bipolar disorder, and recently with brain phenotypes." (PMID 34210021, 2021). "Multiple common intronic single nucleotide polymorphisms (SNPs) in Cav1.2 (CACNA1C gene) LTCCs have consistently been associated with bipolar disorder and schizophrenia, although the consequences of these polymorphisms for Cav1.2 function remain unknown." (PMID 31921405, 2020). "It is also unclear whether the CACNA1C gene has the same effect on schizophrenia in both Asians and Europeans." (PMID 32770953, 2020). "Second, compared to most of the meta-analysis on CACNA1C and schizophrenia, the current study not only included studies on rs1006737 and schizophrenia but also studies on the association between two other CACNA1C polymorphisms (rs2007044 and rs4765905) and schizophrenia." (PMID 32770953, 2020). "In the brain, voltage-gated calcium channel subunit alpha 1C (CACNA1C), Cav1.2, and CACNA1D, Cav1.3 (common variants in CACNA1C and CACNA1D identified with BD, MDD, or schizophrenia), are the predominant L-type Cav channels and are expressed in various cell types including NPC." (PMID 32425815, 2020). "The present study focused on whether there was an ancestral difference in the effect of the CACNA1C gene rs1006737 on schizophrenia." (PMID 32770953, 2020). "In addition, variants in CACNA1C, NOTCH4 and COMT had been reported to be associated with schizophrenia in GWAS studies." (PMID 32273551, 2020). "A growing body of research supports a key role for CACNA1C in schizophrenia in Europeans." (PMID 32770953, 2020). "In the current study, we investigated CACNA1C rs1006737 in patients with schizophrenia." (PMID 31033230, 2019). "In line with functional enrichment results, CACNA1C, one of the hubs of CC M6 presented in both SFARI and WGS set, in which genetic variation have been associated with ASD, Major Depressive Disorder, Schizophrenia as well as some undiagnosable psychiatric illness." (PMID 31649562, 2019). "Therefore, there is an urgent need to conduct research on American, Oceanian, and African populations to understand the relationship between CACNA1C rs1006737 and schizophrenia in the world's populations." (PMID 31033230, 2019). "We have not addressed directly the role of the CACNA1C schizophrenia risk SNP (rs1006737) to modulate the promoter nor its interaction with EZH2 in this communication." (PMID 29501388, 2018). "Of the other loci that reached genome-wide significance within either the schizophrenia data set or within a joint data set including bipolar disorder patients, four loci were associated with validated mRNA targets of miR-137: TCF4, CACNA1C, CSMD1, and C10orf26." (PMID 30618607, 2018). "The cross-disorder risk gene CACNA1C is strongly implicated in multiple neuropsychiatric disorders, including autism spectrum disorder (ASD), bipolar disorder (BPD) and schizophrenia (SCZ), with deficits in social functioning being common for all major neuropsychiatric disorders." (PMID 29739816, 2018).